MTOR (mechanistic target of rapamycin kinase)
Diseases named in the same sentence as MTOR in open-access papers (continued):
Sharing a sentence is not in itself a finding about the gene and the disease.
gastric cancer (continued). "One is to increase the expression of mTOR mRNA and mTOR by sponging miR-100-5p; the other is that lncRNA HAGLROS interacts with mTORC1 components to activate the mTORC1 signaling pathway and inhibit autosis in gastric cancer cells." (PMID 37313458, 2023). "Moreover, Berberine repressed human gastric cancer cell growth in vitro and in vivo via inhibition of MAPK/mTOR pathway." (PMID 37537191, 2023). "Another study explored the effect of TMPO-AS1 on gastric cancer and showed that TMPO-AS1 facilitated cell proliferation, cell migration, and angiogenesis in gastric cancer cells by targeting the miR-126-5p/BRCC3 axis to regulate the PI3K/Akt/mTOR pathway." (PMID 35040749, 2022). "Our results suggest that LMOD1 can upregulate the expression of FAK, activate the phosphorylation level of the Akt / mTOR pathway, promote EMT in gastric cancer cells, increase cell invasion and migration, and promote the occurrence and development of peritoneal metastasis of gastric cancer." (PMID 35488236, 2022). "In gastric cancer, TTK activates the Akt-mTOR pathway to regulate cell proliferation and apoptosis." (PMID 36158685, 2022). "There are several signaling pathways involved in gastric cancer development and progression, including Wnt/beta-catenin, Hedgehog, TGF-β/SMAD3, MAPK, and PI3K/AKT/mTOR signaling pathway." (PMID 35167648, 2022). "It acts on the Akt/mTOR and JAK/STAT pathways in ovarian and gastric cancers." (PMID 36290632, 2022). "Zhou R’s group reported that gastric cancer patients with PRICKLE1 expression were elevated, which may be because PRICKLE1 affects cytoskeletal reorganization by activating mTOR signaling, thus enhancing migration and invasion of gastric cancer cells." (PMID 36861110, 2022). "In a gastric cancer cell line, treatment with MMF led to an alteration of several cyclins and cyclin kinases at the transcriptional level, indicating an influence on the PI3K/AKT/mTOR pathway." (PMID 35572146, 2022). "Our results provide novel insight that TOB1 might suppress gastric cancer by inducing autophagy, possibly through decreasing phosphorylation and the subsequent activation of the AKT/mTOR signaling pathway." (PMID 35186488, 2022). "In vitro and in vivo experiments verified that LMOD1 could affect the migration ability of gastric cancer cells by regulating the FAK-Akt/mTOR pathway, which can alter the EMT of cells to promote the occurrence of peritoneal metastasis in gastric cancer." (PMID 35488236, 2022). "Additionally, miR-495-3p targets GRP78 and regulates mammalian target of rapamycin (mTOR) to modulate autophagy in MDR cells, thereby sensitizing gastric cancer cells to chemotherapy." (PMID 34149413, 2021). "In gastric cancer cells, CSNK2A1 is involved in cancer progression by stimulating proliferation and invasiveness through the phosphorylation of DBC1/CCAR2 and the PI3K-Akt-mTOR pathway." (PMID 34359939, 2021). "Another study confirmed that exosomal circNRIP1 could be transported between gastric cancer cells and promoted the proliferation, migration and invasion by sponging miR‐149‐5p to activate the AKT1/mTOR signalling pathway." (PMID 34672397, 2021). "The enrichment included the PI3K-Akt and IL-17 signaling pathways, and the network analysis showed that the Zhishi-Baizhu herb pair acted on seven key targets, namely, AKT1, MMP9, IL-6, CCND1, BCL2, MTOR, and MDM2 (where they played a role in treating gastric cancer)." (PMID 34899944, 2021). "Secondly, though simultaneous induction of apoptosis and autophagy were observed in gastric cancer cells by PB2, their complex regulatory interaction and upstream regulatory signaling pathways of Akt-mTOR remains unclear." (PMID 33627124, 2021). "Compared with non-tumor gastric mucosa, the mTOR pathway was activated abnormally in advanced gastric cancer." (PMID 34356619, 2021).
gastric cancer (continued). "A recent study confirmed that exosomal circNRIP1 could be transported between gastric cancer cells and promoted proliferation, migration and invasion by activating the AKT1/mTOR signalling pathway." (PMID 34672397, 2021). "In esophageal squamous cell carcinoma, YAP1 has been shown to upregulate Gli1 30, which is in accordance with our previous study in gastric cancer 30, representing that YAP1 enhances cell migration and proliferation via regulating Gli1 expression through the AKT/mTOR signaling pathway." (PMID 35003351, 2021). "As the mTOR inhibitor was administered after intrahepatic recurrence or detection of de novo gastric cancer in patient No.2 and No.3, it was difficult to infer the effect of mTOR inhibitors on tumor recurrence in these cases." (PMID 34733878, 2021). "In conclusion, BBD may reverse the MDR of gastric cancer cells, induce apoptosis, and promote autophagy via inactivation of the PI3K/AKT/mTOR signaling pathway." (PMID 34306145, 2021). "We identified that OE CM-treated gastric cancer cells had low expression of p-mTOR, p-AKT, and p-70S6K, which illustrated that OE CM may inhibit the AKT/mTOR signalling pathway and attenuate M2-mediated malignant phenotypes." (PMID 32226513, 2020). "We further demonstrated that TIPRL induced phosphorylation/activation of AMPK, which in turn attenuated phosphorylation of mTOR, p70S6K, and 4E-BP1, thereby leading to inactivation of mTOR signaling and subsequent suppression of cell migration/invasion in gastric cancer." (PMID 32719745, 2020). "Therefore, we suspect that METTL3/miR-17-92 cluster activates mTOR pathways by targeting PTEN and TMEM127 in gastric cancer progression." (PMID 33037176, 2020). "Western blot OE CM-treated gastric cancer cells expressed low levels of p-mTOR, p-AKT, and p-70S6K, which illustrated that OE CM may inhibit the AKT/mTOR signalling pathway and attenuate M2-mediated malignant phenotypes." (PMID 32226513, 2020). "In addition, targets within AKT/mTOR and MAPK signaling pathways were analyzed due to their involvement in carcinogenic properties, including gastric cancer proliferation." (PMID 31948009, 2020). "NUCKS knockdown significantly reduced cell proliferation and induced autophagy via mTOR-Beclin1 pathway activation, indicating that NUCKS may be a potential therapeutic target for gastric cancer treatment." (PMID 32958058, 2020). "In conclusion, METTL3/m6A promotes gastric cancer growth and metastasis by facilitating pri-miR-17-92 processing into the oncogenic miRNA cluster and activating the AKT/mTOR pathway by targeting PTEN and TMEM127, which could be targeted by everolimus." (PMID 33037176, 2020). "The relationship or interplay between mTOR and miRNA-199a-3p has been studied in cholangiocarcinoma, gastric cancer, and nonneoplastic C2C12 muscle cells." (PMID 33110474, 2020). "Mechanistic target of rapamycin (mTOR) pathway is essential for the growth of gastric cancer (GC), but mTOR inhibitor everolimus was not effective for the treatment of GCs." (PMID 30866995, 2019). "In addition, NVP-BEZ235 can suppress paclitaxel-resistant gastric cancer, which exhibits increased PI3K/mTOR activity." (PMID 31277692, 2019). "Importantly, we provided a novel regulatory mechanism of ANRIL in gastric cancer, by which ANRIL functioned through miR-99a-mediated modulation of BMI1, involved in the apoptotic pathway, and in Notch and mTOR signal pathways." (PMID 30156609, 2018). "Hence, the results suggest that PEC can act has PI3K/AKT/mTOR pathway inhibitor to regulate the cell cycle arrest, autophagy and apoptosis cell death in PEC treated human gastric cancer cells." (PMID 30096805, 2018). "PEC could be a new anticancer therapeutic agent enhancing the treatment responses for human gastric carcinoma with potential impact on the choice of therapy in the case of inhibitors of PI3K, AKT, and mTOR, which is cancer specific." (PMID 30096805, 2018).
gastric cancer (continued). "In conclusion, CISD2 is down‐regulated in gastric cancer, and its effects on the inhibition of cellular proliferation, metastatic ability, and increased chemotherapy sensitivity are mediated by antagonism to 5‐FU‐induced autophagy through the AKT/mTOR pathway." (PMID 28857517, 2017). "Upon additional drug response testing, dual PI3K (Phosphatidylinositol 3-Kinase)/mTOR and topoisomerase 2A inhibitors displayed up to >100-fold increased activity in hereditary c.1380delA CDH1 gastric cancer cells inducing apoptosis most effectively in cells with deficient CDH1 function." (PMID 28460635, 2017). "Our study also validated that SLC1A5 was an important glutamine transporter which promotes gastric cancer growth, and targeting SLC1A5 might have antitumor effects which partly by the inhibition of mTOR/p-70S6K1 signaling pathway." (PMID 29100325, 2017). "Knockdown of PVT1 could reverse cisplatin-resistance in the resistant gastric cancer cells by regulating the expression of MDR1, MRP, mTOR and HIF-1α." (PMID 29108264, 2017). "Moreover, treatment of 20 nM everolimus dramatically abolished DDX5-induced mTOR/S6K1 activation and gastric cancer cell proliferation." (PMID 28216662, 2017). "A mTOR inhibitor, Everolimus, has displayed potential benefit in advanced gastric cancer in phase II trials; however in phase III trials it did not lead to any significant rising of OS." (PMID 29094049, 2017). "Our study also showed anti-proliferation effects of down-regulation of SLC1A5 in gastric cancer cells (HGC-27 and MGC-803), and this cytostatic consequences could be explained partly by suppressing the mTOR/p-70S6K1 signaling pathway." (PMID 29100325, 2017). "Furthermore, NVP‐BKM120 inhibited mTOR downstream activation, but induced the phosphorylation of AKT and ERK in KRAS mutant gastric cancer cells." (PMID 26715098, 2016). "In addition to cytokine-driven activation of pStat3 signaling, human gastric cancers exhibit alterations in several other signaling pathways, including receptor tyrosine kinase/MAPK and PI3K/Akt/mTOR pathways." (PMID 26859571, 2016). "Regulation of MMP expression by activation of mTOR signalling has been demonstrated for several tumor types, but has thus far not been confirmed in gastric cancer." (PMID 26652716, 2015). "Most of the cancer-related signaling pathways such as JAK/STAT, Wnt, NF-κB, PI3K, mTOR, Hedgehog and Notch pathways were activated in gastric cancer compared with noncancerous tissues based on our data." (PMID 25928635, 2015). "MKN45 cells were chosen for this work because that are derived from a poorly differentiated gastric cancer and express both the respective MMPs and mTOR at baseline without the need for stimulation or transfection." (PMID 26652716, 2015). "Treatment of gastric cancer cells with celastrol significantly inhibited phosphorylation of mTOR, but did not affect total mTOR expression when compared with the control." (PMID 26500453, 2015). "Immunohistochemical analysis was used to evaluate the correlations between GOLPH3, phosphorylated mTOR (p-mTOR), phosphorylated Akt (p-Akt), phosphorylated p70S6 (p-p70S6), phosphorylated 4E-BP1 (p-4E-BP1) and the clinicopathological features of gastric cancer." (PMID 25286393, 2014). "In the current study, we showed that the combination of mammalian target of rapamycin (mTOR) inhibitor RAD001 (everolimus) and Akt inhibitor MK-2206 exerted synergistic cytotoxic effects against low-phosphatase and tensin homolog (PTEN) gastric cancer cells (HGC-27 and SNU-601 lines)." (PMID 24416349, 2014). "In our study, RT-PCR and Western blotting revealed that the mRNA and protein expression levels of p-Akt, p-mTOR, p-4E-BP1 and p-p70S6 in the gastric cancer group were significantly higher than in the para-carcinoma tissues and paired normal gastric tissue groups." (PMID 25286393, 2014).
gastric cancer (continued). "There are many novel compounds available today targeting different molecular pathways of gastric cancer such as HER2, EGFR, MET, FGFR, and PI3K/MTOR, which could potentially be used for the treatment of gastric adenocarcinomas." (PMID 25025766, 2014). "Thus, for some gastric cancer patients harbored oncogenic alterations within the PI3K/Akt signaling pathway, such as PIK3CA amplification, combination therapy with an mTOR or Akt inhibitor should be considered." (PMID 22292935, 2012). "Patients with p-mTOR positive gastric cancer showed significantly shorter disease-free and overall survival rates than those with p-mTOR negative gastric cancer (DFS, 48.9% versus 30.1%; p = .006; OS, 51.1% versus 34.4%; p = .011)." (PMID 20929525, 2010). "This possibility is confirmed by observations that the mammalian target of rapamycin (mTOR), an upstream regulator of HIF, is activated in human gastric cancer, whereas attenuation of PI-3K/Akt/mTOR-mediated signalling by rapamycin effectively blocks HIF-1α in gastric cell lines." (PMID 19564950, 2009). "In terms of signaling pathways in gastric cancer cells, iron ions are involved in the regulation of AKT/mTOR, ERK, NF-κB, STAT3, Wnt, and other pathways, indicating their significant impact on the occurrence and progression of gastric cancer through activation or inhibition of these pathways." (PMID 38370477, 2024). "They found that activated B cells could stimulate the mTOR signaling pathway in CD103+CD8+ Trm cells through the LTα-TNFR2 signaling axis, promoting glycolysis and the secretion of CXCL13 and granzyme B, which in turn kills gastric cancer cells." (PMID 39840050, 2024). "A quintessential example is the phosphoinositide 3-kinase-protein kinase B-mammalian target of rapamycin (PI3K/AKT/mTOR) signaling cascade, an important axis in cancer biology, widely targeted in therapeutic strategies for various cancers including breast, liver, and gastric cancers." (PMID 39678497, 2024). "In gastric cancer (GC), lncRNA HAGLROS inhibits autophagic cell death by competitively sponging miR-100-5p to increase mTOR expression." (PMID 39030557, 2024). "Therefore, PEC PEC is believed to the therapeutic potential for gastric cancer and regulates tumors via pathways such as calcium, MAPK, PI3K/AKT/mTOR, and others, based on LC–MS/MS analysis, GO analysis, and reconfirmation of the expression of 6 genes in cells of AGS-xenograft tumors." (PMID 38361124, 2024). "It is highly expressed in gastric cancer (GC) and promotes the occurrence and metastasis of GC by activating the PI3K/AKT/mTOR signaling pathway both in vitro and in vivo." (PMID 38178183, 2024). "In gastric cancer cells, a complex containing overexpressed circIPO7 blocks the caprin-1-G3BP1 interaction, dissociating caprin-1 and its target mRNAs (EGFR and mTOR) from the ribosome, leading to inhibition of their translation and consequent inactivation of the PI3K/AKT/mTOR pathway." (PMID 38778089, 2024). "Similarly, in gastric cancer, ALDH1A3-mediated 5-fluorouracil resistance was connected to ALDH1A3 effects on gene expression of the mammalian target of mTOR and phosphorylation of mTOR target S6 kinase." (PMID 36672441, 2023). "Indeed, another study has also confirmed that mTOR signaling pathway could regulate AQP3 expression, and overexpression of AQP3 could induce autophagy and promote proliferation and migration of gastric cancer cells." (PMID 38089478, 2023). "In the TCGA gastric cancer dataset, high mTOR activity was observed in the proliferative clusters using reverse phase protein array analysis, and approximately half of HER2-amplified GC showed increased mTOR expression." (PMID 37835462, 2023). "Another recent study found that BCAT1 was able to activate PI3K/Akt/mTOR signalling pathway, contributing to the angiogenesis and tumorigenicity of gastric cancer cells, although we did not observe repression of Akt phosphorylation by knockdown of BCAT1 in SCLC cells." (PMID 35318805, 2022).
gastric cancer (continued). "However, the role and mechanism of PSMC2 regulating mTOR pathway through RPS15A in gastric cancer was not reported." (PMID 35256584, 2022). "The data showed that compared with the control cells, the TOB1-overexpressing gastric cancer cells had a significantly reduced content of p-mTOR (**P = 0.0011), indicating that overexpression of the TOB1 gene may inhibit the phosphorylative activation of mTOR." (PMID 35186488, 2022). "PI3K/AKT/mTOR pathway activation serves a critical role in cell growth, proliferation and cell repair, and has been observed in many types of tumors 37, 38.A previous study demonstrated that activation of the PI3K/AKT/mTOR pathway accelerated the metastasis of gastric cancer." (PMID 35399734, 2022). "Collectively, evodiamine inhibits growth of gastric cancer cells by inducing apoptosis, which might be mediated by activation of caspases and inhibition of mitochondrial apoptosis-related proteins, the FAK/AKT/mTOR pathway, and STAT3 signaling." (PMID 36135210, 2022). "Another study manifested that Quercetin could mediate the Akt-mTOR and hypoxia-induced factor 1 α (HIF-1α) signaling pathways to activate the autophagic process in gastric cancer cells and also restrict gastric cancer cell metastasis by blocking the uPA/uPAR function." (PMID 36471693, 2022). "Interestingly, when we used AKTiVIII (Akt/mTOR inhibitors) combined with narciclasine to treat gastric cancer cells, the conversion level of LC3-II was significantly increased compared with the narciclasine group, while the expression levels of p-AKT and p-mTOR decreased." (PMID 34753517, 2021). "After inhibiting gastric cancer cell KRT17, it inhibits proliferation and metastasis and induces apoptosis, and its mechanism of promoting tumor progression may be mainly regulated by AKT/mTOR signal." (PMID 34157940, 2021). "In addition, gastric cancer cells may undergo apoptosis through the MAPK/ERK, PI3K/Akt/mTOR, Wnt/β-catenin and other signaling pathways." (PMID 34966746, 2021). "Furthermore, the AKT/mTOR targeted therapy has become a hotspot of anti-tumor therapy, with a variety of drugs such as AKT or mTOR kinase inhibitors in clinical development of gastric cancer." (PMID 34830011, 2021). "Interestingly, lncRNA XLOC_006753, which is highly expressed in gastric cancer patients and MDR SGC-7901/DDP gastric cancer cells, could promote resistance to DDP through regulating the PI3K/AKT/mTOR pathway." (PMID 32192494, 2020). "Moreover, a recent study indicated that its downregulation may promote the development of gastric cancer by affecting cell proliferation and migration, as well as activation of the PI3/Akt/mTOR signaling pathway." (PMID 30185791, 2018). "Furthermore, our previous studies using microarray screening and bioinformatics analyses to construct the lncRNA-mRNA co-expression network, showed that some of the gastric cancer-related mRNAs were co-expressed with UCA1 and were involved in the regulation of the PI3K-Akt-mTOR signaling pathway." (PMID 29212166, 2017). "Together, our findings indicate that mTOR pathway is among multiple signaling pathways that mediate trastuzumab resistance in NCI N87 T-R cells, and that mTOR inhibitors may be used to treat trastuzumab resistant, HER2-positive gastric cancer tumors." (PMID 28507275, 2017). "BEZ235 specifically inhibited the PI3K/mTOR axis and exerted notable antiproliferative activity, indicating that PI3K/mTOR signaling pathway may be more crucial for HER2-positive gastric cancer survival, and that intervention of this pathway may offer better therapeutic options." (PMID 26560145, 2015). "However, a direct association between mTOR activation and MMP expression has not been shown for gastric cancer so far." (PMID 26652716, 2015). "In summary, an association between the presence of MMP2 and MMP7 proteins and (p-)mTOR expression in gastric cancer could not be confirmed." (PMID 26652716, 2015).